RNU6-891P (RNA, U6 small nuclear 891, pseudogene)
Gene: Small nuclear RNA gene on chromosome 4 (70,852,130 to 70,852,240, forward strand). Ensembl gene ENSG00000207007.
Homologues: Orthologues: chimpanzee U6 (96% identical), pig U6 (86% identical), dog U6 (81% identical), guinea pig U6 (75% identical), rat LOC120095358 (75% identical), mouse Gm54986 (68% identical). Paralogues in human: RNU6-1042P (91% identical), RNU6-25P (91% identical), RNU6-33P (91% identical), RNU6-38P (91% identical), RNU6-698P (91% identical), RNU6-1 (90% identical), RNU6-2 (90% identical), RNU6-20P (90% identical), RNU6-3P (90% identical), RNU6-42P (90% identical), RNU6-48P (90% identical), RNU6-4P (90% identical), and 1284 more.